MIR4310 (microRNA 4310)
Synonyms: hsa-mir-4310
Gene: MicroRNA gene on chromosome 15 (41,866,495 to 41,866,551, reverse strand). Ensembl gene ENSG00000264850.
Homologues: Orthologues: chimpanzee MIR4310 (100% identical).
Diseases named in the same sentence as MIR4310 in open-access papers:
MIR4310 is named in the same sentence as 1 disease in open-access papers, as found by Europe PMC text mining. Sharing a sentence is not in itself a finding about the gene and the disease.
MIR4310 shares sentences with these, for which no sentence is quoted: cervical cancer (1 paper).